EPO (erythropoietin)
Diseases named in the same sentence as EPO in open-access papers (continued):
Sharing a sentence is not in itself a finding about the gene and the disease.
anemia (continued). "Before elective procedures, pre-existing anaemia should be identified and treated with nutritional interventions, iron or erythropoietin as appropriate." (PMID 29297368, 2017). "In these mice, activating erythropoietin (EPO) signaling is cardioprotective, but this intervention is unrelated to the relief of anemia." (PMID 28850611, 2017). "Patients with advanced CKD encounter anemia due to insufficient erythropoietin (EPO) production by the peritubular fibroblasts of the diseased kidney." (PMID 29137321, 2017). "Several companies are developing HIF-P4H inhibitors, the most advanced one being in phase 3 clinical trials to treat anemia of chronic kidney disease via inducing erythropoietin (EPO) production." (PMID 29222481, 2017). "Erythropoietin is a glycoprotein hormone with the function of regulating the formation of red blood cells in the human body and is commonly used to treat anemia following dialysis for patients with ESRD." (PMID 28798802, 2017). "Correction of anemia would, on the other hand, be expected to lower release of erythropoietin, which has previously been shown to foster tumor cell proliferation, tumor angiogenesis and lymphangiogenesis." (PMID 26872376, 2016). "The most frequent adverse events included fatigue (n = 3), headache (n = 2), anemia requiring blood transfusion and erythropoietin injections (n = 2), and nausea (n = 1)." (PMID 28018760, 2016). "ESAs treatment, especially for recombinant human erythropoietin (r-Hu EPO), has become an indispensable procedure of supportive therapy for cancer patients with anemia." (PMID 26575329, 2016). "We show that the same signal transduction network induced by erythropoietin (EPO), a hormone that is frequently employed to treat anemia in cancer patients, regulates survival of both cell types." (PMID 27494133, 2016). "Approximately, 10–15 % of post-renal transplant patients require an erythropoietin-stimulating agent (ESA) for the treatment of post-transplant anemia." (PMID 27119016, 2016). "Administering erythropoietin stimulating agents (ESAs) to patients with anemia also augments, in peripheral blood, the proportion of young RBCs, which have a lower rate of glycosylation than do old RBCs, thereby altering glycosylated hemoglobin formation." (PMID 26818011, 2016). "Most previous studies of CKD and anemia were conducted in patients with ESRD receiving maintenance dialysis, and many of these studies were conducted shortly after the introduction of erythropoietin for treatment of anemia." (PMID 26823182, 2016). "TVR registration trials prohibited the use of EPO for anemia management, although often experts recommend initiating EPO when Hb levels persist lower than 10 g/dL despite RBV dose reductions." (PMID 27356107, 2016). "To assess the effects of EPO treatment in the 5T33MM mouse model on anemia, we initially measured hemoglobin (Hgb) levels, which as expected were reduced in the MM mice." (PMID 27481313, 2016). "The present study is the largest conducted to date evaluating EPO levels for different etiologies of anemia in the elderly, and in particular AUE." (PMID 27310832, 2016). "It is a clinically important question in light of the reported unwanted side effects by EPO in tumor patients with anemia." (PMID 26575329, 2016). "Anemia is a common complication in patients with chronic kidney disease (CKD) and is primarily caused by declining erythropoietin production in such patients." (PMID 26779906, 2016). "Lung cancer patients frequently suffer from chemotherapy-induced anemia, which can be treated with erythropoietin (EPO)." (PMID 27494133, 2016). "Although it is argued that these beneficial effects of EPO in patients with CHF are related to the correction of anaemia, EPO has also been shown to improve cardiac function independent of the haemoglobin level." (PMID 27561278, 2016).
anemia (continued). "2OG dioxygenases, such as the PHDs and FIH, are amenable to inhibition by small molecules, and PHIs are currently in advanced stages of clinical studies for the treatment of anemia through the HIF-mediated up-regulation of EPO (2, 21, –, 23)." (PMID 27502280, 2016). "In order to compare the EPO levels in each etiology to expected values, we required a reference population of patients with a relatively normal EPO response to anemia." (PMID 27310832, 2016). "Clinically, this finding portrays a new angle of complexity to the decision making process regarding EPO treatment in MM, as well as in other clinical conditions where EPO is the treatment of choice for the accompanying anemia." (PMID 27481313, 2016). "The persistence of anemia might be associated with hemolytic uremic syndrome which occurs in rare cases of severe leptospirosis, probably as a result of the action of leptospiral toxins; and/or the disturbance of erythropoietin production due to renal peritubular function impairment." (PMID 27528203, 2016). "Five patients developed anemia, all of whom required EPO administration and 4 of whom required blood transfusions." (PMID 27195149, 2016). "Anemia is treated either by blood transfusion or by erythropoiesis stimulating agents (ESAs) such as erythropoietin (EPO) alfa or beta." (PMID 27494133, 2016). "There were 50 participants (6.6 %) receiving erythropoietin stimulating agents, including 38 (10.9 %) participants with anemia." (PMID 26823182, 2016). "Erythropoietin (EPO), a glycoprotein, regulates erythropoiesis, and is prescribed for the treatment of anemia." (PMID 27147970, 2016). "UAE is uniquely characterized by low plasma erythropoietin (EPO) concentration compared to the other forms of anemia." (PMID 27826252, 2016). "Anemia due to renal insufficiency is primarily as a result of reduced secretion of EPO by the failing kidneys, and anemia subsequently occurs when creatinine clearance is less than 50 mL/minute." (PMID 27142617, 2016). "Intravenous iron use in cancer related anemia has been popularized with the approval of erythropoiesis-stimulating agents in 1997 in oncology, and iv iron was shown to enhance the response to erythropoietin." (PMID 27542823, 2016). "Although anemia was common in this cohort, treatment with erythropoietin was infrequent, reflective of current practice guidelines." (PMID 26823182, 2016). "Traditionally, administration of recombinant human EPO (rHuEPO) is the most common treatment for anemia." (PMID 27244685, 2016). "During the follow-up period, anemia improved, erythropoietin was thus discontinued and insulin requirement decreased to 105 IU." (PMID 26926587, 2016). "Anemia in patients with chronic kidney disease (CKD) is characterized by reduced renal erythropoietin (EPO) production and decreased red-cell survival." (PMID 26978524, 2016). "Anemia improved progressively, and ultimately the administration of erythropoietin was discontinued." (PMID 26926587, 2016). "Strong graded associations were also observed between greater anaemia severity and lower mean corpuscular Hb (MCH) levels, lower transferrin concentrations as well as higher ferritin, hepcidin and erythropoietin concentrations." (PMID 26792471, 2016). "Anemia in sepsis is observed frequently and has a multifactorial etiology, including a decrease in production of erythropoietin due to inflammatory cytokines release, such as tumor necrosis factor (TNF-α), interleukin-1 (IL-1), and interleukin-6 (IL-6)." (PMID 27737630, 2016). "Erythropoietin (EPO) resistance is one of the most common complications in anemia patients undergoing hemodialysis (HD)." (PMID 26788441, 2016). "Presumably, the anemia leads to upregulation of erythropoietin, which in turn stimulates erythropoiesis." (PMID 26872376, 2016). "Because clotting events happened, it was analyzed if anemia occurred or if the quantity of EPO administered increased." (PMID 27803814, 2016).
anemia (continued). "Because of these ambivalent effects, the treatment of lung cancer patients with EPO in the context of cancer-related anemia is controversially discussed." (PMID 27494133, 2016). "Anemia is influenced by aging, as well as iron, the hematopoietic factor erythropoietin (EPO), vitamin B12, folic acid, and other vitamins." (PMID 27918575, 2016). "Five patients (45%) developed anemia with hemoglobin levels below 6.2 mmol/L and required EPO administration during this time period." (PMID 27195149, 2016). "Large clinical researches aimed at the correction of breast cancer, lung cancer and cervical cancer have raised the question that EPO treatment jeopardized the overall survival rate in cancer patients with anemia." (PMID 26575329, 2016). "Recent studies indicate that the use of erythropoietin to treat anemia in patients with proliferative lesions, besides having positive effects on hematological parameters, has the serious adverse effect of promoting the neoplastic process." (PMID 27543111, 2016). "Two thirds of MM patients suffer from anemia and part of these patients are treated with recombinant human erythropoietin (rHuEPO) e.g.2." (PMID 27481313, 2016). "One can easily conclude what would happen in patients with MM displaying bone diseases who are treated with EPO for their anemia." (PMID 27481313, 2016). "These pathways ultimately culminate in an insufficient renal EPO response and hematopoietic EPO resistance further aggravating anemia in AI." (PMID 27557596, 2016). "Recombinant EPO forms or ESAs have been used to treat anemia in chronic kidney disease and other conditions." (PMID 27119016, 2016). "Briefly, two studies in patients with CKD demonstrated an increase in mean Hb concentration after 12 months of intravenous 1,25(OH)2D administration by 1.0 mg/dL and 1.2 mg/dL, and therefore improved control of anemia with reduced need for EPO." (PMID 25885271, 2015). "In the present work the effect of mild exercise training, coupled to erythropoietin (EPO) administration to prevent anemia, has been tested in tumor-bearing mice." (PMID 26636649, 2015). "Acute rejection results in a sharp decrease in erythropoietin production and anemia at the early stage of renal transplantation." (PMID 25853131, 2015). "This phenomenon is likely due to the fact that EPO ameliorated parasite-induced anemia, reduced TNF-α and IFN-γ production, and decreased neuronal apoptosis, representing a potential therapeutic benefit in cerebral malaria." (PMID 26538835, 2015). "The role of androgens on erythropoiesis is known since 1941 when, before the availability of recombinant human EPO, they represented the main pharmacologic agents in the treatment of anemia of chronic and end-stage renal disease, as well as aplastic anemia." (PMID 26779261, 2015). "Those patients had more symptomatic anemia with increased need of subcutaneous erythropoietin supplement." (PMID 25888020, 2015). "This condition has been reported in humans and, more recently, has increased due to the introduction of EPO biosimilars to treat anemia in some countries." (PMID 26712750, 2015). "Only three patients (1.4%) were on weekly anaemia treatment with erythropoietin and iron sucrose, as recommended by the United States NKF-KDOQI." (PMID 26407219, 2015). "On a first line, EPO administration would prevent cancer-induced anemia and boost exercise effectiveness, counteracting fatigue." (PMID 26636649, 2015). "At higher nitrate doses, however, a partial reversal of this effect occurred; this was accompanied by increased renal erythropoietin expression and stabilization of hypoxia-inducible factors, likely brought about by the relative anemia." (PMID 25422368, 2015). "Anaemia stimulated hypoxia has been shown to increase hypoxia-inducible factor 1 which promotes synthesis of erythropoietin, inducing reticulocytosis." (PMID 26697217, 2015).
anemia (continued). "In vivo experiments with p38 MAPK knockout mice show that mice die in utero or survive owing to severe anaemia due to defective erythropoiesis resulting from reduced erythropoietin (Epo) levels." (PMID 25757360, 2015). "Erythropoietin (EPO) is a hematopoietic hormone produced mainly by adult kidneys and has been routinely used in clinic for nearly 20 y to treat anemia." (PMID 26655840, 2015). "EPO resistance along with chronic inflammation in ESRD create the classical conditions for “anemia of chronic disease” mediated by increased hepcidin levels." (PMID 26445018, 2015). "In humans, the use of recombinant EPO is very common in patients with chronic renal disease and/or those undergoing hemodialysis, because various forms of anemia are common in these cases." (PMID 26538835, 2015). "Despite the proven efficacy of r-HuEPO, advancement in the treatment of anemia through the development of longer-acting erythropoietin analogues has been expected." (PMID 26694377, 2015). "Eleven patients (26%) in group A and 17 patients (13%) in group B needed erythropoietin therapy because of symptomatic anemia." (PMID 25888020, 2015). "Ribavirin dose was reduced at week 24 to 200 mg/week in one patient (P4) because of very severe anemia, despite receiving high doses of recombinant erythropoietin." (PMID 26257919, 2015). "The anti-rHuEPO antibodies inhibited both endogenous and recombinant EPO, leading to the development of anemia." (PMID 26712750, 2015). "Renal dysfunction, neurohormonal activation, and proinflammatory cytokines in heart failure enable the development of anemia of chronic disease, with defective iron utilization, inappropriate erythropoietin production, and depressed bone marrow function." (PMID 25710019, 2015). "Anemia in ESRD patients results from the reduced kidney production of erythropoietin (EPO) and changes in iron homeostasis which can lead to iron deficiency." (PMID 25802835, 2015). "The most well-known cause of CKD anemia is an inadequate erythropoietin (EPO) production; however, several events associated with the disease, including chronic inflammation, blood loss, vitamin deficiencies, decreased iron absorption and utilization, might contribute also to the anemia of CKD." (PMID 26712750, 2015). "The depression of serum erythropoietin level is inappropriate given the severity of anemia in CKD patients." (PMID 26694377, 2015). "Being the pathogenesis of cachexia a multifactorial process, it is likely that EPO and exercise act on different targets, improving anemia and muscle strength, respectively." (PMID 26636649, 2015). "The newborn developed anemia and moderate hyperbilirubinemia which required erythropoietin injection and phototherapy." (PMID 26682081, 2015). "The presence of these antibodies has been inferred to cause immune suppression and anemia In particular, anti-EPO autoantibodies have been found in 20% to 41% of untreated HIV patients and are associated with impaired erythropoiesis and HIV-associated anemia." (PMID 26599070, 2015). "Anemia and moderate hyperbilirubinemia were noted five days after birth and successfully treated with phototherapy and erythropoietin injection." (PMID 26682081, 2015). "Although erythropoietin has been used for decades in the treatment of anemia, data regarding endogenous levels in the general population are scarce." (PMID 25915923, 2015). "In mice with chronic kidney disease-associated anemia, combined subtherapeutic doses of EPO and IGF-1 had a comparable effect to a single therapeutic dose of EPO on Hb concentrations." (PMID 26779261, 2015). "It was anticipated that pharmacological replacement with human recombinant erythropoietin (r-HuEPO) would stimulate erythropoiesis and correct the anemia." (PMID 26694377, 2015). "Recombinant human EPO is intensively studied as therapeutic agent for anemia in oncology, renal disease and HF." (PMID 25915923, 2015).
anemia (continued). "In this regard, the most obvious therapeutic implication of PHD inhibitors is that they can be used to treat anemia by enhancing EPO secretion via upregulation of HIF-1α." (PMID 26610437, 2015). "For instance, in vivo studies have shown that recombinant human EPO (rHuEPO) administration increases the efficacy of radiotherapy by reducing anaemia and tumour hypoxia." (PMID 25544764, 2015). "The most effective pharmacological treatment for anemia is erythropoietin (EPO), an endogenous cytokine/hormone able to stimulate erythropoiesis." (PMID 26636649, 2015). "Accordingly, profound anemia occurs even in patients who are adequately treated with erythropoietin and thus have normal reticulocyte numbers in circulating blood." (PMID 25821808, 2015). "Microvascular and macrovascular complications of diabetes can be explained by anemia further deteriorating tissue hypoxia, which is the main stimulus of endogenous erythropoietin (EPO) release." (PMID 25894587, 2015). "Currently there are three options in the treatment of anaemia: blood transfusion, erythropoietin stimulating agents (ESA) and iron supplementation." (PMID 26123286, 2015). "Anemia related to chronic kidney disease (CKD) is characterized by loss of endogenous EPO production and/or EPO hyporesponsiveness/resistance in the patients." (PMID 25853131, 2015). "We were unable to obtain sufficient information to examine precisely the etiology of anemia including iron metabolism, erythropoietin productivity and responsiveness, and inflammation." (PMID 25884723, 2015). "Among these genes, erythropoietin (EPO), PDGF, and transferrin are of particular interest in exploring the link between iron deficiency anemia and bone health." (PMID 25849944, 2015). "In the current cohort study of diabetic patients which were mainly in CKD stages 2 and 3, we found that anemia was common and hepcidin levels were related to endogenous EPO levels and impaired kidney function." (PMID 25894587, 2015). "The purpose of the current study was to investigate hepcidin-25 levels in the setting of diabetic patients with CKD with a focus on its association with EPO levels and other variables of CKD, anemia and inflammation." (PMID 25894587, 2015). "0.4 mg of folic acid and 150 mg of polyferose each day and 300 IU of erythropoietin (EPO) twice a week were applied to alleviate anemia." (PMID 26370296, 2015). "Recombinant Human Erythropoietin (rHuEPO) has been used to reduce the need for RBC transfusion in the treatment of chemotherapy-induced anemia." (PMID 25598955, 2014). "The reduction of EPO expression is believed to be responsible for the occurrence of anemia in the gentamicin model, and in this respect the model resembles the renal anemia observed in patients with CKD." (PMID 25392999, 2014). "The study confirms the finding that younger children produce higher levels of erythropoietin compared to older children with a similar degree of anaemia (Hb levels)." (PMID 25138388, 2014). "According to the theory, EPO's central role would be not only to stimulate the production of new RBCs in conditions of anaemia, as maintained by the orthodox view, but also that of a cytoprotective factor for circulating young RBCs." (PMID 24592241, 2014). "Treatment with recombinant human erythropoietin (rHuEPO) achieves correction of these types of anemia; however, 5–10% of CKD patients develop resistance to the erythropoietic stimuli of rHuEPO." (PMID 25580431, 2014). "In patients with CKD, anemia develops due to decreased renal erythropoietin synthesis resulting from tubulointerstitial damage." (PMID 24967628, 2014). "The thrust of this study was therefore to investigate the level of erythropoietin and haemozoin in both severe malaria anaemia and uncomplicated malaria in Ghanaian children." (PMID 25138388, 2014). "The cloning and production of recombinant human EPO has led to its clinical use in patients with anemia for two and half decades and has facilitated studies of EPO action." (PMID 24918289, 2014).